ABALON (apoptotic BCL2L1-antisense long non-coding RNA )
Gene: Long non-coding RNA gene on chromosome 20 (31,721,507 to 31,723,409, forward strand). Ensembl gene ENSG00000281376.
Diseases named in the same sentence as ABALON in open-access papers:
ABALON is named in the same sentence as 4 diseases in open-access papers, as found by Europe PMC text mining. Sharing a sentence is not in itself a finding about the gene and the disease. The quoted sentences say what the papers report.
liver cancer (1 paper, 2022). An epithelial or non-epithelial malignant neoplasm that arises from the liver. "Among these lncRNAs, levels of eight lncRNAs (ARHGAP5‐AS1, LINC00152, C1QTNF1‐AS1, LINC00969, USP27X‐AS1, NDUFB2‐AS1, TEN1‐CDK3 and ABALON) are markedly associated with the prognosis of TCGA liver cancer (LIHC) patients." (PMID 36354136, 2022).
lung adenocarcinoma (1 paper, 2021). A carcinoma that arises from the lung and is characterized by the presence of malignant glandular epithelial cells. "In this study, we found that high expression of ITGB1-DT, ABALON as well as TMPO-AS1 and low expression of VIM-AS1 in lung adenocarcinoma were associated with poor prognosis." (PMID 33968781, 2021).
malignant tumor (1 paper, 2021). "We selected the malignant tumor-specific SE-regulated gene A2M and the conservative SE-regulated gene ABALON as representatives and displayed the H3K27ac signal distribution on the two loci by IGV in the eight common malignant tumor cell lines." (PMID 34722892, 2021).
ABALON also shares sentences with these, for which no sentence is quoted: tumor (1 paper).